SEC14L3 (SEC14 like lipid binding 3)
Description:
Probable hydrophobic ligand-binding protein; may play a role in the transport of hydrophobic ligands like tocopherol, squalene and phospholipids.
Synonyms: TAP2
Tractability: No criterion of Open Targets' tractability assessment is met for any kind of drug.
Gene: Protein-coding gene on chromosome 22 (30,447,959 to 30,472,056, reverse strand). Ensembl gene ENSG00000100012.
Gene Ontology:
Cellular component: extracellular exosome; cytoplasm
Genetic constraint (gnomAD): Loss-of-function variants: 53 observed, 54.19 expected, observed/expected ratio (o/e) 0.98, 90% interval 0.78 to 1.23. The upper end of that interval is the gene's LOEUF score, 1.23, which puts it in group 5 of 6, group 1 being the genes least tolerant of losing a copy. Missense variants: 467 observed, 505.1 expected, observed/expected ratio (o/e) 0.92, 90% interval 0.86 to 1. Synonymous variants: 161 observed, 195.07 expected, observed/expected ratio (o/e) 0.83, 90% interval 0.73 to 0.94.
Homologues: Orthologues: macaque SEC14L3 (99% identical), chimpanzee SEC14L3 (99% identical), mouse Sec14l3 (97% identical), rat Sec14l3 (90% identical), pig SEC14L3 (86% identical), rabbit SEC14L3 (79% identical), zebrafish sec14l8 (66% identical), zebrafish sec14l7 (59% identical), Drosophila melanogaster CG13893 (29% identical), Caenorhabditis elegans T23G5.2 (28% identical), Caenorhabditis elegans ctg-1 (27% identical), Drosophila melanogaster retm (25% identical), and 2 more. Paralogues in human: SEC14L2 (77% identical), SEC14L4 (70% identical), SEC14L6 (67% identical), SEC14L1 (32% identical), SEC14L5 (32% identical), TTPA (18% identical).
Diseases named in the same sentence as SEC14L3 in open-access papers:
SEC14L3 is named in the same sentence as 10 diseases in open-access papers, as found by Europe PMC text mining. Sharing a sentence is not in itself a finding about the gene and the disease. The quoted sentences say what the papers report.
asthma (4 papers, 2017 to 2024). "Another study identified significant difference in the expression of CRTC1 and its target gene SEC14L3 in asthma, suggesting that CRTC1 plays a regulatory role in bronchial asthma or other lung diseases." (PMID 38644501, 2024). "Sec14-like 3 (Sec14l3) - a putative target of Creb1 - was down-regulated in both asthma models and in NHBE cells upon IL13 treatment, while it’s expression correlated with ciliated cell development and decreased along with increasing goblet cell metaplasia." (PMID 28383034, 2017). "Moreover, an examination of gene expression data showed that CRTC1 and its target gene, SEC14L3, were differentially expressed in individuals with asthma, suggesting that CRTC1 may play a role in regulating conditions such as bronchial asthma or other lung diseases." (PMID 38644501, 2024).
lung carcinoma (1 paper, 2022). "Single-cell transcriptomics of lung cancers reveals that SEC14L3 and APCDD1L were also enriched in monocyte." (PMID 36189290, 2022).
cancer (1 paper, 2024). A tumor composed of atypical neoplastic, often pleomorphic cells that invade other tissues. "KEGG annotations revealed that SEC14L3 knockdown leads to increased alterations in cancer and is closely associated with signal transduction." (PMID 39425205, 2024). "SEC14-like 3 (SEC14L3) has emerged as a compelling target for cancer intervention; nevertheless, the precise clinical implications and molecular underpinnings of SEC14L3 in ccRCC remain elusive." (PMID 39425205, 2024). "Emerging evidence suggests that SEC14L3 may play a pivotal role in the development and progression of human cancers." (PMID 39425205, 2024).
tumor (1 paper, 2024). "Further clinicopathological analysis revealed a correlation between high SEC14L3 expression and advanced tumor grade and pathological stage." (PMID 39425205, 2024). "Collectively, these findings underscore the potential of SEC14L3 as an effective tumor biomarker in ccRCC, and offer valuable insights for prognostic assessment and clinical management." (PMID 39425205, 2024). "Xenograft tumor models revealed discernible tumor growth inhibition in cells with diminished SEC14L3 expression, as evidenced by reduced tumor volumes and weights compared to those in the NC group." (PMID 39425205, 2024). "In summary, our analysis of the TCGA database revealed a significant correlation between elevated SEC14L3 expression and tumor grade and pathological stage in ccRCC patients." (PMID 39425205, 2024). "Intriguingly, our analysis revealed a significant increase in SEC14L3 expression in the T3&4 tumor grade group relative to that in the T1&2 group." (PMID 39425205, 2024). "Reduced NFKB1 in NFκB impedes SEC14L3 promoter and enhancer activation, forming a positive feedback loop that enhances tumor suppression." (PMID 39425205, 2024). "Prior to investigating the impact of SEC14L3 on the cellular phenotype of ccRCC, we assessed SEC14L3 protein expression levels in 12 pairs of clinically matched tumor and adjacent tissue samples." (PMID 39425205, 2024). "Then we analyzed SEC14L3 expression in GSE53757 dataset from GEO database and discovered that SEC14L3 was significantly upregulated in tumor tissues compared to adjacent non-tumor kidney tissues." (PMID 39425205, 2024).
SEC14L3 also shares sentences with these, for which no sentence is quoted: allergic asthma (1 paper); ciliopathies (1); clear cell renal cell carcinoma (1); Hypertension (1); infection (1); lung diseases (1).